IL10 (interleukin 10)
Diseases named in the same sentence as IL10 in open-access papers (continued):
Sharing a sentence is not in itself a finding about the gene and the disease.
alcohol dependence (8 papers, 2017 to 2025). Physical and psychological dependence on alcohol. "A single nucleotide polymorphism in the IL-10 gene is associated with decrease expression of IL-10 and is linked to alcoholism." (PMID 34202246, 2021). "Dennis and colleagues (2018) also found that PTSD symptom severity is associated with higher IL-10 levels, which are then mediated by vagal activity, smoking, and alcohol dependence." (PMID 31991875, 2020). "Preclinical research has demonstrated that IL-10 deficiency exacerbates hepatic inflammation and hepatocellular injury in mice, while stimulating IL-10 production in HSCs and KCs can prevent alcohol-induced liver damage." (PMID 40399593, 2025). "A decrease in IL-10 protein abundance was observed after alcohol dependence in male mice, and (low) IL-10 and (high) IL-1β was positively correlated with baseline alcohol intake." (PMID 37601537, 2023). "Although in both groups IL-10 is only expressed in about 0.1% of CD45+ cells, we investigated the potential for increased anti-inflammatory responses in alcohol dependent mice." (PMID 33347446, 2020).
allergic conjunctivitis (8 papers, 2011 to 2023). "Patients with allergic conjunctivitis demonstrate an immunological dysregulation, characterized by the low expression of IL-10 and an inverted tear IL-10/TNF-α ratio." (PMID 37020645, 2023). "This work aims to evaluate the potential involvement of IL-10+ B cells in allergic conjunctivitis and their impact on ocular changes." (PMID 30818819, 2019). "Data which are in accordance with an in vivo study in a rodent model, which report that IL-10 attenuates allergic conjunctivitis by protecting from mast cell activation/degranulation, instead of affecting its numbers in the conjunctiva." (PMID 24699261, 2014). "In addition, IL-4, IFN-γ, and IL-10 were elevated in active seasonal allergic conjunctivitis and vernal keratoconjunctivitis." (PMID 35160111, 2022). "Tanaka and Alfonso demonstrated that Sema3a suppressed the release of Th2-related cytokines (IL-5, IL-13 and IL-4) and inflammatory cytokines (IFN-α, IL-17 and TNF-α) but increased levels of the cytokine IL-10 in experimental allergic conjunctivitis and autoimmune arthritis models." (PMID 29975739, 2018). "Our findings demonstrate an immunological dysregulation in patients with allergic conjunctivitis, characterized by the low expression of IL-10 in circulating CD19+CD38+ Bregs subsets, and an inverted tear IL-10/TNF-α ratio." (PMID 30818819, 2019). "Our findings demonstrate an immunological dysregulation in patients with allergic conjunctivitis, characterized by the low expression of IL-10 in circulating CD19+CD38+ Bregs subsets and an inverted tear IL-10/TNF-α ratio, promoting a local pro-inflammatory microenvironment." (PMID 30818819, 2019). "A study reported increases in IL-1β, IL-2, IL-5, IL-6, IL-12, IL-13, in seasonal allergic conjunctivitis (SAC), vernal keratoconjunctivitis (VKC) and atopic keratoconjunctivitis (AKC), while IL-4, IFN-γ and IL-10 levels were increased in SAC and VKC compared to controls." (PMID 21298010, 2011).
amyotrophic lateral sclerosis (8 papers, 2015 to 2022). Amyotrophic lateral sclerosis (ALS) is a neurodegenerative disease characterized by progressive muscular paralysis reflecting degeneration of motor neurons in the primary motor cortex, corticospinal tracts, brainstem and spinal cord. "In a transgenic model of amyotrophic lateral sclerosis, IL-10+ regulatory B cells adoptive transfer therapy could effectively reduce the number of bone marrow-derived macrophages in the central nervous system." (PMID 33343576, 2020).
ANCA-associated vasculitis (8 papers, 2016 to 2022). "IL-10–deficient regulatory T cells lose their capacity to attenuate renal tissue injury in CrGN17 and low intracellular IL-10 levels in remission were associated with a high relapse rate of ANCA-associated vasculitis during the long-term follow-up26." (PMID 35715470, 2022). "Analysis of individuals with the variant allele and ANCA-associated vasculitis showed a decrease in IL-10 production, which is known to exhibit anti-inflammatory properties." (PMID 30871019, 2019). "Also, a reduced number of IL-10 producing cells in ANCA-associated vasculitis was shown in a study by Wilde et all." (PMID 30053822, 2018). "Several studies have examined IL10 production in patients with ANCA-associated vasculitis (AAV)." (PMID 27044386, 2016).
Arrhythmia (8 papers, 2015 to 2025). Any cardiac rhythm other than the normal sinus rhythm. "Various cytokines have been linked to arrhythmia, including TNF-alpha, Interleukin-6, Interleukin-8 and Interleukin-10 (IL10)." (PMID 34830025, 2021). "Further studies are required to determine whether IL-10 has a modulating function in arrhythmias." (PMID 41574188, 2025).
ascariasis (8 papers, 2012 to 2024). An infection that is caused by the roundworm Ascaris lumbricoides, many cases of which remain asymptomatic. "The treatment of ascariasis has been associated with a decline in levels of plasma IL-10." (PMID 22848773, 2012). "Earlier, in 2006, a study on ascariasis and toxocariasis in India utilized a commercial ELISA to test 46 patients and 19 controls for various cytokines including IL-10." (PMID 25888883, 2015). "This study found that patients with both infections as well as those with ascariasis only had significantly higher IL-10 levels than healthy controls." (PMID 25888883, 2015). "Albendazole treatment during Ascaris lumbricoides infection might decrease worm load leading to a reduction in IL-10 production, which ultimately improved cellular immunity and CD4+T cell counts." (PMID 28761478, 2017). "Since Al-CPI induces the production of IL-10 and TGF-β, this may partially explain the antibody profile induced during ascariasis." (PMID 37887050, 2023). "In our study, statistically significant higher IL-10 values were found in children with ascariasis, although they did not correlate with infection intensity of this parasite." (PMID 27882241, 2016). "This study showed that children with ascariasis had significantly higher IL-10 serum concentrations than non-infected controls." (PMID 25888883, 2015).
babesiosis (8 papers, 2016 to 2025). Babesiosis refers to a condition caused by microscopic parasites that infect the red blood cells. "Decreased IL-10 serum concentration on the seventh day of babesiosis caused by B. canis was also observed." (PMID 36839438, 2023). "We observed a similar pattern: higher MCP-1 levels in complicated cases and increasing levels of IL-8 in the period studied (day 1 to 7), in remarkable contrast with the decrease observed in B. rossi-induced babesiosis, and a similar or slightly lower IL-10 concentration associated to complications." (PMID 29304171, 2018). "In dogs, IL-10 impairs neutrophil function during babesiosis, and in humans, PD-L1+ myeloid cells are major IL-10 producers in several cancers." (PMID 41488614, 2025). "Relatively high and similar expression of IL-10 was found in dogs with mild/moderate and severe babesiosis." (PMID 36739305, 2023). "Furthermore, the expression of Th1 and Th2 cytokines/transcription factors in dogs with babesiosis was also accompanied by a relatively high and similar expression of regulatory IL-10." (PMID 36739305, 2023). "Our current study suggested that immunization with rBmSP44 elicits IFN-γ, TNF-α, and IL-10 expression and results in a Th1/Th2 mixed humoral and cellular immune response, which may contribute to protect mice from Babesia infection." (PMID 32733477, 2020). "Ingenuity Pathway Analysis indicated that interleukin-17 facilitated the secretion of Th2 cytokines, such as interleukin-10, -4, and -6, thereby inducing a predominately Th2 protective immune response and promoting the expression a high level of special IgG1 against Babesia infection." (PMID 29312230, 2017). "IL-6 and IL-10 support the secretion of Th2 cells, which simultaneously activate B cells to induce systemic immune responses and produce antibodies to protect against Babesia infections." (PMID 29312230, 2017). "It seems probable that in this disease, as in bovine babesiosis, early increased production of IL-18 and IL-12 stimulates the release of IFN-γ and TNF-α, leading to activation of iNOS and NO production, which together with delayed secretion of IL-10 causes oxidative damage to erythrocytes." (PMID 36839438, 2023). "We observed resolution of babesiosis caused by B. microti despite significant increase in plasmatic TNFα level but it was not as high as reported for WA1 strain, which could be attributed to simultaneous increased production of IL-10 and its anti-inflammatory activity." (PMID 29445365, 2018). "Alternatively, negative correlations between IL-10 and both hematocrit and the number of RBCs have been observed in B. canis-infected dogs, but only in uncomplicated babesiosis." (PMID 36839438, 2023).
brain tumors (8 papers, 2016 to 2025). "Based on the results of studies that investigated the association between the gene IL-10 and the development of brain tumors, CNS alterations, and other types of cancers, it is possible that changes in gene expression influence disease." (PMID 36009467, 2022). "In contrast, numerous studies have supported the utility of elevated CSF IL-10 in distinguishing PCNSL from other brain tumors, neuroinflammatory conditions, and systemic DLBCL." (PMID 40881684, 2025). "Numerous studies have been conducted to link the gene IL-10 to other types of brain tumors, cancer, and CNS diseases." (PMID 36009467, 2022). "Currently, there are insufficient studies on the IL-10 gene in CNS diseases and brain tumors, especially PA." (PMID 36009467, 2022). "Recent studies further showed that brain tumor cells induced pericytes to secrete high levels of immunosuppressive cytokines, such as IL-10 and TGFβ, suggesting that intimate cross-talk between GBM cells and pericytes reprogram GBM-associated pericytes to acquire immunosuppressive properties." (PMID 33308315, 2020). "In high grade brain tumors, Tregs suppress activation, proliferation and cytokine production of CD4+/CD8+ T cells via secreted cytokines such as TGF-B and IL-10 or via cell-to cell contact mediated by the constitutively expressed CTLA-4 and PD-L1 checkpoints." (PMID 30974896, 2019). "Elevated CSF IL-10/IL-6 ratio (the thresholds including: ≥0.21, ≥0.72, ≥1, and ≥1.6) could identify PCNSL patients from infection of CNS, other brain tumors, and systemic NHL patients." (PMID 40881684, 2025). "Compared to group with other brain tumors, patients with PCNSL had higher serum IL-10 level." (PMID 40881684, 2025). "Furthermore, T-cell PCNSL and other brain tumors/metastases also had TAM infiltration, but the CSF IL-10 level was negligible in these cases." (PMID 27924864, 2016).
chronic asthma (8 papers, 2016 to 2024). An asthma that is characterized by the development of persistent airway inflammation and recurrent attacks of breathlessness and wheezing, which vary in severity and frequency. "Montelukast sodium statistically elevatesthe serum level of anti-inflammatory protein IL-10 and reduces peripheral bloodeosinophils following a 4-week treatment, providing clinical benefits for childrenwith chronic asthma." (PMID 32520202, 2020). "We previously showed that IL-32γ modulates immune responses by recruiting IL-10-producing monocytic cells in a chronic asthma model." (PMID 30257681, 2018). "Previous studies showed that immunotherapy ameliorated airway inflammation via IL-10 in a chronic asthma model." (PMID 28978148, 2017). "In addition, our results demonstrated an increase in the levels of the main pro-inflammatory cytokines found in chronic asthma (IL-4, IL-5, and IL-13) and reduced the anti-inflammatory IL-10." (PMID 35185864, 2021). "Interestingly, the use of Gal-3 therapy has also shown positive results on murine models simulating chronic asthma, with a significant reduction in key BAL cytokines like IL-5, interleukin-4 (IL-4), and interleukin-10 (IL-10)." (PMID 38785528, 2024).
chronic rhinosinusitis (8 papers, 2016 to 2024). Chronic form of sinusitis. "One study showed a downregulation of CD8+T-cells via IL-10 as a novel pathophysiologic mechanism of chronic rhinosinusitis." (PMID 34208325, 2021). "A recent study has reported that electroacupuncture suppresses the decrease in the expression of interferon-γ, alleviates mucosal damage caused by inflammation, and shows a synergistic beneficial effect when combined with interleukin-10 (i.e., overexpression) in a mouse model with chronic sinusitis." (PMID 36091598, 2022).
common variable immunodeficiency (8 papers, 2006 to 2025). "Another study on common variable immunodeficiency showed that Breg were defective in IL-10 expression and that the frequency of IL-10-producing CD24hiCD38hi or CD24hiCD27+ B cells was decreased when the cell culture contained CpG." (PMID 30917149, 2019). "RA has been shown to normalize the proliferation of defective B cells and restore their IgG-producing capacities as well as IL-10 production in the presence of TLR9/CD180 stimulation in common variable immunodeficiency (CVID) models." (PMID 30081517, 2018). "A bias towards Th2-mediated immune response was also documented in patients with common variable immunodeficiency (CVID) through investigation of cytokine levels and demonstration of increased IL-4 and IL-10 production." (PMID 21918651, 2012).
coronary atherosclerosis (8 papers, 2018 to 2025). Atherosclerosis of the coronary vasculature. "Furthermore, the hyper-regulation of IL-10 was significantly linked with an increased risk for future cardiovascular and coronary atherosclerosis." (PMID 36298704, 2022). "While the role of Th2 cells in atherogenesis remains debated, it has recently been shown that patients with coronary artery atherosclerosis had an impaired Treg/Th17 ratio together with reduced serum levels of IL-10." (PMID 30583563, 2018).
dysplasia (8 papers, 2015 to 2026). A usually neoplastic transformation of the cell, associated with altered architectural tissue patterns. "However, our inverse associations with dysplasia are consistent with a previous study that found that IL‐2, IL‐5, IL‐8, IL‐10, IL‐13 and TNF‐alpha tend to be downregulated in low‐grade/moderate dysplasia of the pancreas compared to serous cystadenoma without dysplasia." (PMID 39482824, 2025). "OSCC had significantly more IL-10+, but not more IL-4+ cells, than OLP and OLK tissues, while the number of IL-4+, but not IL-10+ cells, increased gradually with the progression of dysplasia in OLK tissue." (PMID 28053372, 2016). "However, we did not observe a positive correlation between the number of IL-10+ cells and the progression of dysplasia in OLK patients." (PMID 28053372, 2016).
endometrial cancer (8 papers, 2020 to 2024). Primary or metastatic malignant neoplasm involving the endometrium (mucous membrane that lines the endometrial cavity). "Given the scarcity of data on these proteins in endometrial cancer, this study aims to evaluate the diagnostic potential of preoperative serum concentrations of IL-4, IL-7, IL-9, IL-10, NT, TSP-2, and NRP1." (PMID 39334861, 2024). "Taken together, we demostrate that CD146+CAFs can promote progression of endometrial cancer by inducing angiogenesis and vasculogenic mimicry via IL-10/JAK1/STAT3 pathway." (PMID 38459564, 2024). "We also showed that CD146+CAFs promoted the progression of endometrial cancer by inducing angiogenesis and VM via the IL-10/JAK1/STAT3 pathway in vitro and in vivo exploration." (PMID 38459564, 2024). "2- sample MR analysis indicated suggestive causal relationships of inflammatory cytokines, such as IL-10 (OR = 0.919; P = 0.049), Eotaxin (OR = 0.927; P = 0.047), IFN-γ (OR = 0.852; P = 0.009) and SCGF-β (OR = 1.064; P = 0.044) on endometrial cancer risk." (PMID 39020272, 2024). "In endometrial cancer, IL-10 has been shown to promote epithelial–mesenchymal transition (EMT) and vascular mimicry, which are processes associated with tumor progression, suggesting a possible role in assessing tumor aggressiveness and patient outcomes." (PMID 39334861, 2024). "Western blot analysis revealed that IL-10 promoted EET in endometrial cancer cells in a concentration-dependent manner." (PMID 38459564, 2024). "The maximum IL-10 signal in the endometrial cancer group was higher than in the benign group, with shifts of 15.30 ± 6.22 nm versus 8.13 ± 2.57 nm, respectively." (PMID 39759973, 2024). "They fabricated LSPR silver nano structure-based immune sensor and detected cytokine IL-10 in the serum of individuals with endometrial cancer." (PMID 39759973, 2024). "Taken together, these findings suggest that STAT3 can directly activate CDH5 transcription by binding to its promoter region in endometrial carcinoma and that IL-10 can further promote transcription." (PMID 38459564, 2024). "In the case of endometrial carcinoma, progesterone exertion was suspected to inhibit anti-inflammatory cytokines production, which was confirmed for IL-10 and excluded for IL-37." (PMID 36769226, 2023). "Activated CD8+ TIL in endometrial cancer barely produced IL-13 (1.06%), but they did produce GM-CSF (median 26.08%) and, to a lesser extent, IL-21 (median 8.79%) and very little IL-10 (median 3.7%)." (PMID 32471032, 2020). "Taken together, these results provide evidence that CD146+CAFs could promote the progression of endometrial cancer by inducing angiogenesis and VM formation via the IL-10/JAK1/STAT3 pathway." (PMID 38459564, 2024). "Our study aimed to determine whether IL-4, IL-7, IL-9, IL-10, NT, TSP-2, and NRP1 could be diagnostic markers for endometrial cancer in women." (PMID 39334861, 2024). "We also found that the expression of IL-10 is correlated with OS in endometrial cancer patients." (PMID 38459564, 2024). "The numbers of VM were significantly greater in specimens from patients with high IL-10 expression than in those from patients with low IL-10 expression, indicating that IL-10 may stimulate the formation of VM in endometrial cancer." (PMID 38459564, 2024). "In addition, compared with that in the normal endometrium, the expression of IL-10 in endometrial cancer was increased, indicating that it may be a tumorigenic cytokine in endometrial cancer." (PMID 38459564, 2024). "IL-10 promoted epithelial-endothelial transformation (EET) and further VM formation in endometrial cancer cells via the janus kinase 1/signal transducer and activator of transcription 3 (JAK1/STAT3) signalling pathway." (PMID 38459564, 2024). "This study showed that IL-10 and TSP-2 should not be used as diagnostic markers in endometrial cancer." (PMID 39334861, 2024).
endometrial cancer (continued). "The purpose of this study was to determine if IL-4, IL-7, IL-9, IL-10, NT, TSP-2, and NRP1 could be used as novel, helpful markers for the detection of endometrial cancer." (PMID 39334861, 2024). "Finally, we evaluated the significance of IL-4, IL-7, IL-9, IL-10, NT, TSP-2, and NRP1 in the diagnosis of endometrial cancer." (PMID 39334861, 2024). "In the case of endometrial carcinoma, estradiol action was suspected to inhibit IL-10, but not IL-37 anti-inflammatory cytokines production." (PMID 36769226, 2023).